EGFR (epidermal growth factor receptor)
Diseases named in the same sentence as EGFR in open-access papers (continued):
Sharing a sentence is not in itself a finding about the gene and the disease.
tumor (continued). "An intriguing observation in our study was that, initially, EGFR CAR T cells displayed a pronounced proliferation at the tumor site followed by a decay of the bioluminescent signal indicating a reduction of intratumoral CAR T cells in the second half of the therapy." (PMID 35836798, 2022). "EGFRvIII is a common tumor-specific splice variant of EGFR present in human tumors, found in 30% of newly diagnosed GBM cases and second in EGFR alteration frequency only to wild-type EGFR amplification." (PMID 35603165, 2022). "Pyrrolidine could specifically target the cytosolic phospholipase A2 (cPLA2α) along with EGFR antibody and offer better targeting specifically to the tumour site, resulting in a higher uptake of the nanorattles than non-targeted nanorattles." (PMID 35875329, 2022). "In advanced tumours with distant diseases, the combination of chemotherapy with immunotherapy against the epidermal growth factor receptor (EGFR) or the vascular endothelial growth factor (VEGF) has achieved satisfactory outcomes in terms of increased survival." (PMID 35454384, 2022). "Different subgroups were assessed for risk scores based on age, gender, tumor location, survival status, T-stage, tumor stage, EGFR mutation status and KRAS mutation status, wherein all the subgroups had significant differences except the tumor location and EGFR mutation status subgroups." (PMID 36498802, 2022). "In this regard, we have to also consider that by stopping the EGFR-TKI treatment due to the progression of the disease, there is a risk of a rebound tumor flare, which can occur in about 20% of the patients, and may play a role in treatment choice." (PMID 35159099, 2022). "Therefore, to improve the prognosis of patients with EGFR-mutation NSCLC, the development of novel treatments that offer the possibility to inhibit tumor growth and invasion is particularly important." (PMID 36230634, 2022). "Nimotuzumab is an intermediate affinity anti-EGFR antibody that inhibits cell proliferation and angiogenesis, activates natural killer cells, stimulates dendritic cell maturation, induces cytotoxic T cells, and restores MHC-I expression on tumor cells, hindering one of the EGFR immune-escape ways." (PMID 35800050, 2022). "HBc capsid proteins were genetically modified by inserting His6-spacer peptide-Tyr6 at the N-terminus and replacing Pro79Ala80 with the tandem repeat of the affibody peptide for human epidermal growth factor receptor I (EGFR), which is overexpressed in various tumor cells." (PMID 36714624, 2022). "Third, data on tumor mutation burden, including oncogenic drivers other than EGFR/ALK, were not reported." (PMID 35747163, 2022). "On the other hand, due to the significant role of epigenetics in the regulation of EGFR, evaluation of EGFR expression in tumor samples could be more informative than genetic testing." (PMID 35565444, 2022). "We hypothesized that CTCs and inflammatory markers (using NLR and dNLR) are surrogates of response to EGFR-targeted therapy that may be used as biomarkers and complement the use of circulating tumor DNA (ctDNA) in the diagnosis and prognosis of NSCLC patients." (PMID 36292049, 2022). "Through downstream effectors such as the Ras/Raf/MAPK and PI3K/Akt/mTOR signaling pathways, EGFR activation could induce tumor cell proliferation and survival." (PMID 35903366, 2022). "The aim of this study was to identify whether erlotinib moiety assists in tumor targeting through interaction with EGFR and whether this interaction inhibits EGFR kinase activity." (PMID 36232384, 2022).
tumor (continued). "The statistically significant association between EGFR phosphorylation and GABP expression in tumor tissue led us to hypothesize that EGFR activation of the mutant TERTp is mediated by transcriptional upregulation of one or more GABP subunits." (PMID 36130485, 2022). "In addition, tumor glucose and glutamine metabolism were reported to stimulate PD-L1 expression via EGFR and ERK/C-Jun signaling pathways." (PMID 36291769, 2022). "However, like other targeted therapies, EGFR-TKIs lead to acquired resistance, and eventual tumor relapse compromises overall patient survival, highlighting the urgent need to develop new strategies for circumventing drug resistance." (PMID 36048538, 2022). "Several studies demonstrated that PD-L1 expression on immune cells were less affected by tumor cell intrinsic factors, such as EGFR activation, and might be a better biomarker." (PMID 35990690, 2022). "A possible explanation may be that NSCLC with rare EGFR mutations had higher levels of PD-L1 expression and more abundant CD8+ tumor-infiltrating lymphocytes (TILs) infiltration." (PMID 35990690, 2022). "In continuation of our efforts in the discovery of EGFR-2 inhibitors, we designed and synthesized a new theobromine derivative as a potential compound that may exert a marked EGFR inhibitory activity and consequently inhibit the growth of tumor cells." (PMID 36144596, 2022). "However, only 5% of the patients achieve dramatic initial responses (>90% tumor reduction) to treatment, and moreover, most of them eventually become resistant to EGFR inhibitors." (PMID 35565351, 2022). "The expression of PD-L1 in EGFR-mutant NSCLC may result from the activation of the cell-intrinsic EGFR pathway instead of cell-extrinsic stimulation from the tumor immune microenvironment." (PMID 36581631, 2022). "Several drugs targeting EGFR have been developed and approved to treat tumor patients." (PMID 36059616, 2022). "Models containing the postoperative clinicopathological characteristics, including Ki‐67 levels, EGFR mutation, and tumor differentiation, were valuable for patients who did not have a detailed pathological report." (PMID 35289087, 2022). "Using this probe, they map activation of EGFR signalling during tumour treatment." (PMID 35105871, 2022). "While it is not clear how specific these results are to HDF cells in particular, the consistency of our observations here clearly indicate that hinge-truncated CARs would have lower overall sensitivity to EGFR in all contexts and thus lower likelihood of on-target off-tumor toxicity." (PMID 35935988, 2022). "The acquisition of mesenchymal morphology in relapsed tumours is distinct from EGFR-TKI resistance." (PMID 35932303, 2022). "Moreover, EGFRxSIRPα significantly delayed tumour growth of EGFR‐positive A431 cells compared to treatment with EGFR mAb or rhSIRPα." (PMID 35908284, 2022). "Moreover, most of those molecules showed poor tumor-suppressive effects in pre-clinical studies under concentrations of 100 μM, which render our EGFR candidates powerful interviewees in the current market." (PMID 35884571, 2022). "EGFR signaling is one of the most studied cellular pathways involved in tumor progression." (PMID 35884464, 2022). "We performed multivariate Cox regression analysis and differential analysis of gene expression between the tumour and precancerous tissue on 11 prognostic Ras-related genes, and we got three differently expressed prognostic Ras-related genes (EGFR, RAP1B and PDGFRA)." (PMID 35281814, 2022). "Notably, we show that neutralization of ATG16‐L1 β restores EGFR‐TKIs‐induced apoptosis in resistant cells through induction of autophagy and limits tumor growth." (PMID 35593080, 2022). "EGFR was also positively correlated with the levels of serum tumor markers (P < 0.001)." (PMID 35582197, 2022).
tumor (continued). "It is recognized that tumor cells liberate more exosomes than normal cells and that the surface of TDEs contains membrane proteins, such as EGFR, CD317, CD91 as well as PD-L1, which might represent potential tumor markers." (PMID 36556468, 2022). "Resistance to third-generation EGFR inhibitors mediated by EGFR-independent mechanisms can develop through the activation of alternative bypass pathways and abnormal downstream signal transduction closely related to tumor growth, invasion and metastasis." (PMID 35840984, 2022). "EGFR also activates ARF6 to stimulate oncogenic Ras tumor overgrowth by regulating Hh signaling." (PMID 36224181, 2022). "Since IKK16 also inhibits IKKα which has an NF-κB-independent role, regulation of tumor suppressor genes may be mediated by EGFR-IKKα in TNBC cells." (PMID 36358633, 2022). "With regard to the tumour suppressor function of MAGL, it was shown in this context that MAGL can inhibit the transactivation of epidermal growth factor receptor (EGFR)-associated signalling pathways as well as proinflammatory proteins such as COX-2 and tumour necrosis factor (TNF)-α." (PMID 35277658, 2022). "Target inhibition of EGFR expression can induce tumor cell death." (PMID 35672352, 2022). "To develop a vaccine that targets individualized neoantigen in NSCLC patients with EGFR mutations who do respond to ICIs, we performed a retrospective analysis of 1862 Chinese NSCLC tumor tissues matched with normal tissue samples which were previously profiled using our 1021-gene panel." (PMID 36505399, 2022). "During this transition, dependence on AR is often lost, and enhanced EGFR-mediated signaling may promote tumor progression." (PMID 35804847, 2022). "From a meta-analysis published in 2017 covering all first line studies, a significant predictive benefit was demonstrated for chemotherapy plus EGFR antibody therapy in patients with left-sided tumours (HR 0.75 [95% CI 0.67-0.84] and 0.78 [95% CI 0.70-0.87] for OS and PFS, respectively)." (PMID 36300092, 2022). "In addition, tumor-derived exosomes have also been identified to contain corresponding tumor biomarkers, such as EpCAM, PD-L1, and EGFR." (PMID 35281563, 2022). "Therefore, miR-7 was proposed as a potential tumor suppressor because it is capable of regulating several related oncogenes in the EGFR pathway." (PMID 36012357, 2022). "Moreover, EGFR signaling induces angiogenic factors from mesenchymal stem cells in tumors and regulates tumor cell migration." (PMID 36085020, 2022). "We then identified 4924 tumor cells (63.7% of the total cell population), characterized by a chromosome 7 gain and chromosome 10 loss, via inference of single-cell CNV state 5,10,11 and gene expression markers SOX2, PTPRZ1, and EGFR." (PMID 35941215, 2022). "Considering the improved benefits of NCT03513666A and the IMpower150 trial, a promising treatment was to combine ICIs with chemotherapy to improve the immunogenicity of tumor cells or anti-angiogenesis to promote more TIL infiltration into the tumor in EGFR-mutant NSCLC." (PMID 35935943, 2022). "Under hypoxic conditions, the expression of CAIX (carbonic anhydrase IX) regulated through EGFR/STAT3/HIF-1α axis significantly increased in GBM, contributing to the polarization of tumor-associated monocytes/macrophages (TAM) toward a more tumor-supportive phenotype." (PMID 35600367, 2022). "Five patients demonstrated vaccine induced CD8+ T cell responses against epidermal growth factor receptor (EGFR) neoantigen peptides, showing that personalized neoantigen vaccination is a feasible and safe method to increase immune response against tumor cells harboring EGFR mutations." (PMID 36059606, 2022). "Targeting the EGFR with SMIs is a suitable validated strategy in tumor therapy." (PMID 35402265, 2022). "Moreover, these researchers reported tumor growth suppression by EGFR-redirected CAR-Ts in cell line-established and PDX preclinical mouse models." (PMID 36483567, 2022).
tumor (continued). "Overexpression of other receptor tyrosine kinases, including HER2, HER3, MPM7, and coexpression of all four HER family member (HER1, HER2, HER3, HER4) receptors, also may contribute to tumor resistance to EGFR-targeting agents." (PMID 36143274, 2022). "The results of EGFR mutation by tumor tissue re-biopsy were the same as those of liquid biopsy in the three patients who were positive for major EGFR mutations and negative for the T790M mutation by liquid biopsy at PD (100%)." (PMID 36192767, 2022). "ADCs can precisely target tumor cells by combining highly specific monoclonal antibodies with highly toxic cytotoxic drugs, thereby achieving a precise attack on EGFR-TKI-resistant cancer cells and filling the gap between antibody drugs and traditional chemotherapy drugs." (PMID 35840984, 2022). "Therefore, we used the tumor-specific DNA of extracellular vesicles (EVs) in bronchoalveolar lavage fluid (BALF) as DNA source for EGFR genotyping." (PMID 35681723, 2022). "Moreover, EGFR CAR T cell-treated tumors displayed the highest T cell density within these tissues indicating that there was the strongest anti-tumor and proliferative response ongoing." (PMID 35836798, 2022). "In addition, 2-DG was combined with the EGFR inhibitor gefitinib to inhibit PD-L1 expression and PD-1/PD-L1 binding from enhancing anti-tumor immunity." (PMID 36558902, 2022). "Vascular endothelial growth factor (VEGF), basic fibroblast growth factor (BFGF), matrix metalloproteinase (MMP), epidermal growth factor receptor (EGFR), and angiopoietin are important factors promoting tumor angiogenesis and play an important role in the development and progression of tumor." (PMID 35528244, 2022). "Moreover, EGFR inhibition in tumour cells induced T-cell proliferation and activation, thus promoting an enhanced immune response in tumours treated with the TKI erlotinib." (PMID 36010935, 2022). "A large variety of EGFR-targeting antibodies, antibody mimetics and peptides has been developed to be used as homing devices with cytotoxic agents in order to reduce systemic side effects of anti-tumor drugs." (PMID 35269611, 2022). "Therefore, targeting persistent tumor cells during early EGFR-TKI therapy is a goal of new therapeutic strategies to prevent the development of overt EGFR-TKI-resistant tumors." (PMID 36612121, 2022). "Thus, effective control of the expression of JAK/STAT3 and PI3K/AKT by EGFR contributes to the regulation of the growth and apoptotic state of tumor cells." (PMID 35190747, 2022). "Moreover, it was evident that tumour hypoxia was required to upregulate EGFR protein expression in hypoxic cancer cells." (PMID 35681586, 2022). "Near-infrared (NIR)-tagged antibodies against EGFR have shown promise by improving tumor-to-background signal compared to existing methods, but this approach suffers from production and purification issues as well as the need for creating species-specific analogs." (PMID 36082359, 2022). "Several reports have indicated that the clinical benefits of EGFR-targeting agents may be mediated not only by direct suppression on the growth of tumor cells, but only by regulation on the tumor microenvironment." (PMID 35641479, 2022). "However, osimertinib has now become the standard of care for the first-line treatment of EGFR-mutant NSCLC and it was recently approved for use in the adjuvant setting following tumor resection in patients with EGFR-mutant NSCLC." (PMID 35326725, 2022). "Moreover, the anti-tumor efficacy of sotorasib is enhanced by the EGFR inhibitor cetuximab, as the drug combination significantly reduces cell viability in vitro and potently suppresses tumor growth in a patient-derived xenograft (PDX) model." (PMID 36483040, 2022). "This indicates that CDCA can act as an EGFR inhibitor and potentiate anti-tumor drugs effect." (PMID 35252007, 2022). "This downstream pathway activation may provide a synergism with EGFR for tumor cells to escape from EGFR TKI inhibition." (PMID 35756605, 2022).
tumor (continued). "In our study, only 50% of patients with EGFR-mutant tumors had another EGFR-mutant tumor." (PMID 35740676, 2022). "Based on that, we speculate if FBXW2 represses tumor growth and metastasis of PCa through regulating EGFR." (PMID 35499593, 2022). "Importantly, we report the first orthotopic xenograft tumor models of DSRCT and demonstrate significant reduction in tumor burden with EGFR-targeted therapies." (PMID 34841430, 2022). "However, upon treatment of a subset of erlotinib conjugates with therapeutic light, EGFR-inhibitory activity is recovered that is effective in attenuating EGFR kinase activity and EGFR signal-dependent tumor cell proliferation." (PMID 36232384, 2022). "Detection of EGFR T790M status in 201 paired plasma ctDNA and tumor tissues by ddPCR." (PMID 36776375, 2022). "However, KSTAR predicts that the tumor has significant levels of both EGFR and ERBB2 activity, similar to WHIM35 and WHIM8, which also respond to lapatinib treatment." (PMID 35879309, 2022). "It has been proposed that EGFR-TKI combination therapy may limit tumor development and regulate the acquisition of resistant variants." (PMID 35304574, 2022). "Additionally, plasma ACh levels and tumor ChAT expression highly correlated with response to EGFR-TKI and progression-free survival in human NSCLC patients." (PMID 36048538, 2022). "These patients may be attributed to the tumor heterogeneity and the aberrant expression of driver genes, such as CDKN2A mutation or EGFR amplification." (PMID 35267417, 2022). "Hence, monitoring the activation of EGFR-related signaling pathways can help reveal the progression of tumor development." (PMID 35105871, 2022). "Compared with non-selective TKIs originally developed for EGFR mutations, these novel TKIs have shown greater activities and broader anti-tumor effects across exons in HER2-mutant NSCLC." (PMID 35425713, 2022). "In addition, the clinical tumor response and a longer duration of EGFR-TKI treatment (≥12 months) were reported to be associated with a higher frequency of T790M mutation acquisition." (PMID 35205720, 2022). "Furthermore, HCP-LCE demonstrated specific cellular binding properties on EGFR/PD-L1 double-positive tumor cells." (PMID 35479092, 2022). "Likewise, in patient-derived xenograft HCC models with high EGFR levels, the combination provoked noticeable tumor control and was well tolerated by the models." (PMID 36080304, 2022). "Importantly, these aberrations can coexist in the same tumor and with EGFR-TKI tertiary mutations, which are the basis for the complexity and heterogeneity of cancer evolution in response to EGFR-TKI treatment." (PMID 35840984, 2022). "In addition, it has been shown that EGFR mutations influence TME components, such as tumor-infiltrating lymphocytes (TILs), Tregs, MDSCs, TAMs, and immunoregulatory cytokines." (PMID 35742933, 2022). "In addition, tumor-associated antigens such as prostate stem cell antigen (PSCA), prostate specific membrane antigen (PSMA) and epidermal growth factor receptor (EGFR) are expressed in urologic neoplasms." (PMID 35860578, 2022). "We propose that the focused investigation of tumor cell traits along with the immune features of the tumor is unavoidable in order to understand the drivers of cetuximab resistance, and to choose patients most eligible for the EGFR-targeting therapy regimen." (PMID 35626010, 2022). "Crotoxin may have a high affinity for EGFR, which suggests that crotoxin might modulate the EGFR signaling pathway to exert its anti-tumor activity in SPCA-1 cells." (PMID 36668838, 2022). "As EPP suppressed the STAT3 and MET/AKT pathways, which stimulate tumor growth and confer EGFR TKI resistance, EPP could be applied not only to EGFR TKI-naïve or -sensitive NSCLC, but also to EGFR TKI-resistant NSCLC." (PMID 35408753, 2022).